LEP (leptin)
Diseases named in the same sentence as LEP in open-access papers (continued):
Sharing a sentence is not in itself a finding about the gene and the disease.
Hyperglycemia (continued). "Interestingly, these effects were associated in mice with alterations of leptin action and hyperleptinemia, as well as hyperglycemia, hyperinsulinemia and glucose intolerance." (PMID 24410832, 2014). "Insulin and leptin resistance and elevated levels of ghrelin, mediated by short sleep duration, have been associated with sleep restrictions and increased catecholamine and cortisol levels, and hypoxia can amplify hyperglycemia, negatively affecting these processes." (PMID 37366660, 2023). "Several studies have investigated the association between leptin and renal diseases, Previous experimental animal studies have suggested that higher leptin levels may cause hyperglycemia, elevations in blood pressure (mediated through increased sympathetic activity), and renal dysfunction." (PMID 35619087, 2022). "Importantly, brain leptin infusion was potent in reducing circulating glucose in fasting associated with suppressing counter-regulatory hormone levels, all effects mimicking leptin action on reducing T1D hyperglycemia." (PMID 33976218, 2021). "Thus, leptin-deficient mice with FTO display a hyperglycaemia already early in life." (PMID 25144618, 2014). "Due to the consequential fetal hyperglycemia, insulin, glucose, and leptin signaling in the fetal brain are dysregulated." (PMID 40077761, 2025). "That leptin ameliorates hyperglycemia and ketogenesis via actions that are separable from one another, and involve distinct brain areas, highlights the distributed nature of the brain’s fuel-mobilizing neurocircuitry." (PMID 40759579, 2025). "Hyperglycaemia and insulin excess potentiate leptin-mediated signalling, particularly via IGF1R–Akt–mTOR activation, further accelerating cell cycle progression and biomass accumulation in breast and mammary epithelial cells." (PMID 41586225, 2025). "In addition, maternal hyperglycemia was found to be related to the epigenetic regulation of the neonatal leptin gene by Mendelian randomization analysis, which supported that maternal glucose was one of the causal pathways affecting the epigenetic regulation of leptin in offspring." (PMID 41488068, 2025). "Regarding the mechanism by which leptin ameliorates hyperglycemia, previous studies have reported that leptin acts on hypothalamic neurons to inhibit hepatic gluconeogenesis and to promote glucose uptake in BAT and muscle via autonomic nervous system pathways." (PMID 40429740, 2025). "In mice with IDDM, leptin treatment alone had a limited effect on improving hyperglycemia, but co-administration of leptin and liraglutide improved glucose metabolism to levels comparable to those of healthy mice." (PMID 40429740, 2025). "Another study has shown that leptin protects against hyperglycemia-induced neural damage by inhibiting Bax/Bcl-2 ratio." (PMID 38980528, 2025). "Hyperglycemia, lipid accumulation in tissues, chronic low-grade inflammation, elevated leptin levels, endothelial dysfunction, and impaired mitochondrial function can lead to increased production of reactive oxygen species (ROS)." (PMID 41149623, 2025). "Maternal hyperglycemia can induce metabolic alterations, including greater glycemic variability, dysregulated hormone secretion (e.g., adipokines and leptin), and chronic low-grade inflammation." (PMID 41156099, 2025). "The first involves hyperglycemia; this begins with increased food intake due to increased leptin resistance due to increase leptin levels, which in turn block insulin secretion, leading to the onset of hyperglycemia." (PMID 40356974, 2025). "It has been shown that leptin concentration decreases with long-term hyperglycemia and, therefore, long-lasting hyperglycemia promotes the maintenance of appetite by lowering leptin concentration." (PMID 38396961, 2024). "High fasting hyperglycemia is known to affect leptin levels in diabetics with insulin insufficiency, reducing blood levels of leptin." (PMID 38707092, 2024).
Hyperglycemia (continued). "Leptin also plays a crucial role in modulating glucose homeostasis; it has been shown to reduce hyperglycemia in ob/ob mice, and leptin administration has successfully restored glucose homeostasis in patients with lipodystrophy." (PMID 39125589, 2024). "This syndrome affects IR through adipokine dysregulation, where altered adipokine secretion (e.g., elevated leptin and reduced adiponectin) fosters systemic inflammation and leptin resistance, leading to hyperglycemia." (PMID 39744182, 2024). "Key adipokines such as leptin, resistin, and ghrelin disrupt insulin signaling, inhibit glucose receptor activity, and contribute to hyperglycemia." (PMID 39596980, 2024). "Compared to women with isolated fasting hyperglycemia, women with isolated postload hyperglycemia had a lower leptin concentration (53.2 vs 64.1 ug/L; P = .003), consistent with their lower BMI." (PMID 36950879, 2023). "For instance, some studies have established a connection between elevated leptin concentrations and hyperglycemia, a rise in blood pressure, natriuresis, and renal dysfunction." (PMID 36698704, 2023). "Maternal hyperglycemia in insulin-dependent diabetes during pregnancy enforces the fetal pancreas to release insulin that increases fetal and placental leptin concentration in paracrine and induces fetal overgrowth and macrosomia." (PMID 37854189, 2023). "In fact, central leptin can rescue T1DM hyperglycemia and recently, another mechanism has been proposed for this action." (PMID 36674935, 2023). "PTP1B inhibits leptin signaling, and mice with T1DM induced by streptozotocin show hyperglycemia and reduced glucose metabolism, and leptin administration improves glucose metabolism in these mice." (PMID 36674935, 2023). "Mice with the elevated expression of a major antioxidant selenoprotein (GPX1) showed hyperglycemia, hyperinsulinemia, elevated body fat accretion and plasma leptin and reduced insulin sensitivity." (PMID 36978903, 2023). "In leptin-deficient mice, FASN ablation alleviated hepatic steatosis and improved glucose tolerance but exacerbated fed hyperglycemia and liver dysfunction." (PMID 37681411, 2023). "This is achieved by averting hyperglycemia through stimulation of a leptin-mediated satiety response." (PMID 36516750, 2022). "A number of studies have reported placental epigenetic changes in maternal hyperglycemia via candidate gene approach measuring proximal promoter region methylation levels in metabolic health-relevant genes (e.g. leptin, adiponectin, lipoprotein lipase)." (PMID 35721735, 2022). "Leptin promotes fibrosis primarily on the glomerulus but can potentially prevent/reverse renal injury by normalizing metabolic disturbances, including hyperglycemia and hyperlipidemia." (PMID 36160448, 2022). "Compared with the offspring from NC dams, the offspring from HF dams exhibited a higher body weight, hyperglycemia, glucose intolerance, hyperinsulinemia, hypercholesterolemia, and leptin resistance and lower adiponectin at weaning." (PMID 35928844, 2022). "Those who have the homozygous dominant, 'AA' form of the leptin gene exhibited hyperglycaemia as compared to other genotypes." (PMID 36128550, 2022). "Another ob/ob model, in which the leptin mutation is found in an insulin-resistant BTBR strain, is the BTBR ob/ob, leading to early T2DM development and maintenance of hyperglycemia, compared with other ob/ob models, as the animal become overweight/obese." (PMID 35409324, 2022). "Leptin deficiency contributes to IR and abnormal metabolism in other settings: leptin therapy corrects hyperglycemia in diabetic mice and lipodystrophy patients." (PMID 36176462, 2022). "Hyperglycemia/Hyperinsulinemia:Insomnia-(pw8b)-central nervous system-(pw25)-(pw66)-↑ghrelin:leptin-(pw67)-↑insulin resistance-(pw72)-liver-(pw14)-↑blood glucose-(pw55)-↑Hyperglycemia/Hyperinsulinemia." (PMID 35252372, 2022).
Hyperglycemia (continued). "Several studies demonstrated the existence of an adipoinsular axis, characterized by leptin-inhibited insulin synthesis and secretion, promoting hyperglycemia, as shown in our model." (PMID 34578791, 2021). "Our data suggest that leptin action on T1D LepRArc neuron inhibition and hyperglycemia is mediated by reversal of energy deprivation in T1D LepRArc neurons." (PMID 33976218, 2021). "Together, these data demonstrate that leptin action on reducing T1D hyperglycemia is mediated through reversing energy deprivation in LepRArc neurons, leading to inhibition of these neurons, and reduced counter-regulatory responses." (PMID 33976218, 2021). "Our results identify aberrant activation of LepRArc neurons owing to energy deprivation as the neural basis for T1D hyperglycemia and that leptin action is mediated by inhibiting LepRArc neurons through reversing energy deprivation." (PMID 33976218, 2021). "Leptin action on reducing T1D hyperglycemia is reversed by nutrient deprivation or activation of nutrient deprivation signaling pathways." (PMID 33976218, 2021). "We chose ob/ob mice as recipients, because these mice lack expression of functional leptin and thus develop a severe metabolic phenotype that is easy to monitor, i.e., increased bodyweight, hyperglycemia, and hyperinsulinemia." (PMID 34198579, 2021). "Obese mice also have hyperglycemia and hyperleptinemia, indicating the presence of glucose intolerance and leptin resistance." (PMID 34489970, 2021). "Both acute and chronic activation of GABAArc neurons reversed leptin action on reducing T1D, while inhibition of these neurons was sufficient to produce leptin-mimicking action on reducing T1D hyperglycemia." (PMID 33976218, 2021). "We found that active smoking induced hyperglycemia and significant reductions in serum insulin and leptin levels." (PMID 34917518, 2021). "To further address this and specifically examine the effect of 2-DG in the brain, we tested the effect of i.c.v injection of 2-DG on leptin’s ability to reduce T1D hyperglycemia." (PMID 33976218, 2021). "The main causes of functional changes in the male reproductive system in T2DM are postprandial hyperglycemia, insulin and leptin resistance, inflammation, elevated production of the reactive oxygen and nitrogen species, oxidative stress and lipotoxicity." (PMID 35008624, 2021). "In the DM group, hyperglycemia was associated with increased levels of pro-inflammatory cytokines (TNF-α and IL-6), MDA, and leptin." (PMID 35008523, 2021). "The same study used NOD mice that were severely diabetic and systemic leptin gene therapy resulted in a remarkable improvement in hyperglycemia and ketosis and improved body weight for nearly 6 months." (PMID 34947993, 2021). "The present results indicate that active smoking not only induced aberrations in the oral and gastrointestinal microbiomes, but it also led to hyperglycemia, reduced serum insulin and leptin levels." (PMID 34917518, 2021). "Because leptin increases peripheral glucose uptake and corrects hyperglycemia when directly infused into the VMH, it is possible that the effects observed in Rap1ΔSF1 mice are due to enhanced sensitivity of leptin." (PMID 33974562, 2021). "Emerging studies have demonstrated that, in addition to its role in body weight regulation, adipocyte-derived leptin is capable of reducing T1D hyperglycemia in an insulin-independent manner." (PMID 33976218, 2021). "In the group treated with MEL, a reduction in hyperglycemia, pro-inflammatory cytokines, and leptin, and increased levels of adiponectin, an anti-inflammatory adipokine, were observed." (PMID 35008523, 2021). "Our results demonstrate that GABAergic LepRArc neurons mediate T1D hyperglycemia and leptin action on reducing T1D glucose." (PMID 33976218, 2021).
Hyperglycemia (continued). "Depressive symptoms can develop directly from hyperglycemia (related to increased oxidative stress, inflammation, or leptin resistance induced by hyperglycemia), and indirectly from psychological stress related to the diagnosis of diabetes." (PMID 31936358, 2020). "Probably the mechanism of Zn effect in reducing hyperglycemia in obese and/or diabetic animals is due to increased leptin expression induced by this mineral." (PMID 32405346, 2020). "We examined blood glucagon levels in RIP-CreΔLEPR-LEP, however, i.c.v. leptin injection lowered blood glucagon in insulin-deficient RIP-CreΔLEPR mice, while RIP-CreΔLEPR-LEP still showed hyperglycemia." (PMID 33071988, 2020). "The mechanism of osteoporosis in db/db mice is complicated, such as hyperglycemia, AGEs, abnormality of renin-angiotensin system, and leptin." (PMID 32080264, 2020). "They showed the reduction of insulin and leptin sensitivity, alteration of neuropeptide expression, hyperglycemia and compromised β-cell function." (PMID 32948162, 2020). "In our previous study, we showed that an exposure to maternal hyperglycemia during pregnancy likely modulated neonatal leptinemia, partially through changes in cord blood LEP DNAm levels." (PMID 31947745, 2020). "Leptin administration prevented the development of hyperglycaemia in the obese offspring of both sexes." (PMID 31703240, 2020). "In this study, we provide novel evidence supporting the mediating effects of placental LEP DNAm dysregulation in response to maternal hyperglycemia during pregnancy on neonatal leptin levels, a proxy for adiposity at birth." (PMID 31947745, 2020). "SLC9A1 has been shown to be required for the increased adhesion, migration, and phagocytosis of oxidized LDL seen in monocytes in response to stimuli including leptin, adrenaline, and hyperglycemia." (PMID 31615550, 2019). "As expected, although both ob/ob and db/db mice displayed severe hyperglycemia and hyperinsulinemia, only db/db mice developed hyperleptinemia, while circulating leptin levels were below detection range for ob/ob mice." (PMID 30374710, 2018). "HFD feeding induced hyperglycemia and increases in plasma insulin and leptin levels, whereas plasma triglyceride were unchanged." (PMID 29686414, 2018). "According to previous studies, anthocyanins have a suppressive role in the development of adipocyte hypertrophy and reduce hyperglycaemia in HF mice, and cyanidins induced leptin and adiponectin production in isolated adipocytes." (PMID 30363947, 2018). "This downregulation is also in line with the fact that high plasma insulin and leptin levels are usually present concomitant with hyperglycaemia and high fat mass, respectively, that is, during periods of excess supply of nutrients." (PMID 28421113, 2017). "One study found that 19–28% of variability in offspring LEP methylation was explained by maternal hyperglycemia, leaving the quantitatively largest portion to be explained by other factors." (PMID 28413567, 2017). "Collectively, these data support that glucocorticoids excess itself in CRF-OE is responsible for the elevated circulating levels of leptin and insulin and the hyperglycemia." (PMID 28101317, 2017). "Leptin supplementation improved hyperglycemia on days 5 to 7 and reduced food intake and water consumption in OSI-906-treated mice." (PMID 28646158, 2017). "Previous reports from Unger and others have highlighted dramatic improvements in diabetic symptoms (severe hyperglycemia and ketosis) with exogenous leptin administration to T1DM mice." (PMID 27581061, 2016). "Both mouse models suggest loss of insulin-mediated intra-islet suppression of glucagon production, and with this in mind, we have made a preliminary exploration of leptin treatment in Akita mice, intended to suppress the hyperglycemia with hyperglucagonemia." (PMID 28702245, 2016).
Hyperglycemia (continued). "Regarding adipocytokine replacement, the use of recombinant leptin in hypoleptinemic patients with lipodystrophies gives very promising results, with marked improvement in hyperglycaemia, hypertriglyceridemia, and hepatic steatosis." (PMID 25885670, 2015). "Hidaka and colleagues found that leptin injection into the third cerebral ventricle also improves hyperglycemia in a similar animal model." (PMID 25870537, 2015). "Of note, i.c.v. leptin treatment reverses hyperglycemia and permits survival of DT-treated RIP-DTR mice." (PMID 25870537, 2015). "Ten-week-old WT and PRLR−/− mice injected with leptin antagonist presented fasted hyperglycemia compared to control saline injected mice." (PMID 24667351, 2014). "Leptin was shown to promote glucose mobilization during SW transfer in tilapia, indicating a hormone-driven hyperglycemia under a hyperosmotic challenge." (PMID 25520040, 2014). "The hypouricemia is also consistent with the hyperglycemia and observed changes in insulin, leptin and adiponectin." (PMID 24839967, 2014). "Increased bone expression of osteotesticular protein tyrosine phosphatase (ESP or OST-PTP) also occurred with HYP mice consistent with the observed hyperglycemia and abnormal insulin/leptin levels." (PMID 24839967, 2014). "Recent preclinical results indicate that different types of hypothalamic neurons are endowed with the ability to mediate the hyperglycemia-lowering action of the adipocyte-derived hormone leptin in an insulin-dependent and insulin-independent fashion." (PMID 24589844, 2014). "A definite crosstalk between hyperglycemia and leptin signaling exists in breast epithelial cells, as well as, other cells types throughout the body." (PMID 24260287, 2013). "Recombinant methionyl human leptin (r-metHuLeptin) has been reported to be useful in controlling hyperglycemia, insulin levels, and HbA1c in patients with RMS and other lipodystrophy syndromes." (PMID 23367497, 2013). "The injection of rAAV-lep increases hypothalamic leptin expression and moderates diet-induced hyperglycemia, hyperinsulinemia, and skeletal muscle insulin resistance." (PMID 23579596, 2013). "To our knowledge, we show for the first time that in breast epithelial cells, hyperglycemia alone directly impacts leptin signaling." (PMID 24260287, 2013). "Our results are consistent with the last study, since high levels of leptin were significantly correlated with hyperglycemia, hyperinsulinemia, increased HOMA-IR, and hypertriglyceridemia in our study population." (PMID 23986664, 2013). "Typically, the DIO model is characterized by increased body weight gain, hyperglycemia, and establishment of insulin-resistant state (hyperinsulinemia, increase of the leptin/adiponectin ratio, ectopic fat storage in the liver and muscle)." (PMID 22888363, 2012). "In contrast, serum leptin concentrations at the time of hyperglycemia were universally low in both the case and the control cohort patients (<0.005ng/ml; below the detectable limit of the ELISA; data not shown)." (PMID 22679509, 2012). "The central finding of our study was that very premature infants with severe hyperglycemia had significantly lower circulating adiponectin levels although leptin levels were univserally low in both cohorts." (PMID 22679509, 2012). "When fructose was given in combination with leptin, a rapid and significant increase in fructose-induced hyperglycaemia occurred as soon as 15 min." (PMID 19956534, 2009). "Food restriction in SDT fatty rats induced a temporal improvement of hyperglycemia and an increase of serum leptin and adiponectin level." (PMID 19696902, 2009). "There is evidence that maternal hyperglycaemia can result in chronic fetal hyperglycaemia and hyperinsulinaemia, which increases fetal fat mass and leptin synthesis within the fetal fat deposits." (PMID 19385960, 2009).